KRR1 (KRR1 small subunit processome component)
Description:
Part of the small subunit (SSU) processome, first precursor of the small eukaryotic ribosomal subunit. During the assembly of the SSU processome in the nucleolus, many ribosome biogenesis factors, an RNA chaperone and ribosomal proteins associate with the nascent pre-rRNA and work in concert to generate RNA folding, modifications, rearrangements and cleavage as well as targeted degradation of pre-ribosomal RNA by the RNA exosome.
Synonyms: Rip-1; HRB2
Tractability: Small molecule: a structure with a bound ligand is known. PROTAC: UniProt records ubiquitination sites on it; ubiquitination databases record sites on it; its protein half-life has been measured.
Gene: Protein-coding gene on chromosome 12 (75,490,863 to 75,511,636, reverse strand). Ensembl gene ENSG00000111615.
Subcellular location: Nucleus, nucleolus; Nucleus; Cytoplasm
Subcellular location (Human Protein Atlas): Nucleoli; Nucleoli rim; Mitotic chromosome; Nucleoplasm
Pathways (Reactome):
Metabolism of RNA: Major pathway of rRNA processing in the nucleolus and cytosol; rRNA modification in the nucleus and cytosol
Gene Ontology:
Molecular function: protein binding; RNA binding; nucleic acid binding
Biological process: ribosomal small subunit biogenesis; maturation of SSU-rRNA; ribosome biogenesis
Cellular component: cytoplasm; membrane; nucleolus; nucleoplasm; nucleus; small-subunit processome
Genetic constraint (gnomAD): Loss-of-function variants: 18 observed, 36.26 expected, observed/expected ratio (o/e) 0.5, 90% interval 0.34 to 0.74. The upper end of that interval is the gene's LOEUF score, 0.74, which puts it in group 3 of 6, group 1 being the genes least tolerant of losing a copy. Missense variants: 375 observed, 397.62 expected, observed/expected ratio (o/e) 0.94, 90% interval 0.87 to 1.03. Synonymous variants: 117 observed, 134.31 expected, observed/expected ratio (o/e) 0.87, 90% interval 0.75 to 1.02.
Homologues: Orthologues: chimpanzee KRR1 (99% identical), macaque KRR1 (99% identical), pig KRR1 (93% identical), guinea pig KRR1 (93% identical), mouse Krr1 (92% identical), rat Krr1 (92% identical), rabbit KRR1 (91% identical), tropical clawed frog krr1 (79% identical), zebrafish krr1 (74% identical), Drosophila melanogaster dbe (55% identical), Caenorhabditis elegans krr-1 (47% identical).
Diseases named in the same sentence as KRR1 in open-access papers:
KRR1 is named in the same sentence as 15 diseases in open-access papers, as found by Europe PMC text mining. Sharing a sentence is not in itself a finding about the gene and the disease. The quoted sentences say what the papers report.
polycystic ovary syndrome (3 papers, 2017 to 2021). A disorder that manifests as multiple cysts on the ovaries. "KRR1 encodes proteins present in early 90 S precursor particles of the small ribosomal subunit, and its locus has been implied to contribute to the development of polycystic ovary syndrome." (PMID 34249080, 2021). "KRR1 was reported to be associated with polycystic ovary syndrome (PCOS) in European cohorts." (PMID 30419816, 2018). "A recent genome-wide association study (GWAS) of polycystic ovary syndrome (PCOS) in European cohorts has identified six susceptibility loci mapping to 11q22.1 (YAP1), 2p21 (THADA), 11p14.1 (FSHB), 2q34 (ERBB4), 12q21.2 (KRR1), and 5q31.1 (RAD50)." (PMID 28195137, 2017).
breast carcinoma (2 papers, 2016 to 2023). "During this study, we identified for the first time increased frequency of antibody response toward KRR1 antigen in sera of breast cancer patients and in sera of patients with invasive ductal breast carcinoma compared with sera of healthy women." (PMID 27847402, 2016). "This study aims to confirm cancer-related serological profile of ZRF1 and KRR1 in large-scale ELISA screening of their recombinant analogues with sera of breast cancer patients of different histological types and tumor grades compared with sera of healthy individuals." (PMID 27847402, 2016). "Increased frequency of antibody response was found in sera of breast cancer patients to ZRF and KRR1 antigens." (PMID 27847402, 2016). "Two additional genes, KRR1 and FN1, were only detected in the breast cancer-specific analysis." (PMID 37173324, 2023). "Analysis of antibody response frequency toward KRR1 and ZRF antigens in the sera of breast cancer patients taking into account histological type of tumors showed a statistically significant antibody response only in sera of patients with invasive ductal carcinomas." (PMID 27847402, 2016).
breast tumor (1 paper, 2016). "Here, we studied immunogenicity of 2 out of 18 MBC antigens, namely, ZRF1 and KRR1, in sera of patients with breast tumors of different histological types and grades compared with sera of age-matched healthy donors using large-scale allogeneic screening performed by ELISA." (PMID 27847402, 2016).
jaw cysts (1 paper, 2026). "The identified 6 proteins, namely CD79A, CD5, KRR1, UTP20, AATF, and WDR43 - may be closely associated with the pathogenesis of jaw cysts." (PMID 42175431, 2026).
malignant fibrous histiocytoma (1 paper, 2016). "It was suggested only that KRR1 is associated with metastasis in malignant fibrous histiocytoma." (PMID 27847402, 2016).
medullary breast carcinoma (1 paper, 2016). An infiltrating breast carcinoma with a relatively favorable prognosis. "In this investigation, our attention was focused on two potential tumor-associated antigens, namely, Zuotin-related factor 1 (ZRF1) and R motif-containing protein 1 (KRR1), previously identified by SEREX analysis of medullary breast carcinoma cDNA library." (PMID 27847402, 2016). "Among these immunoreactive autoantigens, there are 2 proteins; in particular, Zuotin-related factor 1 (ZRF1) and R motif-containing protein 1 (KRR1) (clones KY-MBC 29-88-1 and KY-MBC 18-53-1) were identified during the screening of cDNA library from medullary breast carcinoma." (PMID 27847402, 2016).
Obesity (1 paper, 2016). Accumulation of substantial excess body fat. "The genes within 2 Mb of the signal, include RP11-81H3.2, CAPS2, GLIPR1, GLIPR1L1, GRLPR1L2, and KRR1, none of which is an obvious candidate gene for involvement in obesity or T2D." (PMID 27623749, 2016).
tumor (2 papers, 2016 to 2025). "KRR1 is mainly responsible for the formation of the 40S ribosomal subunit and is thought to correlate with drug response and tumor progression, especially in the use of S-1, cisplatin, and docetaxel." (PMID 40191191, 2025).
infection (1 paper, 2016). The state of being infected such as from the introduction of a foreign agent such as serum, vaccine, antigenic substance or organism. "At the second infection stage, we determined that MIR10a regulates HIV-1 proteins including Gag/Pol (p-value < 1☓10-16), which significantly interacts with small subunit (SSU) processome component, homolog (yeast) (KRR1) (p-value < 1☓10-16), also known as HIV-1 Rev binding protein 2 (HRB2)." (PMID 26897165, 2016).
reproductive diseases (1 paper, 2017). "The expression pattern at rs12478601 (THADA locus) in skin and fat, rs804279 (GATA4 locus) and rs1795379 (KRR1 locus) in fat and rs2268361 (FSHR locus) in skin predicted involvement in reproductive diseases." (PMID 28068351, 2017).
KRR1 also shares sentences with these, for which no sentence is quoted: cancer (1 paper); invasive ductal carcinomas (1); lung carcinoma (1); peripheral neuropathy (1); pulmonary arterial hypertension (1).